LEP (leptin)
Diseases named in the same sentence as LEP in open-access papers (continued):
Sharing a sentence is not in itself a finding about the gene and the disease.
Alzheimer disease (continued). "Leptin has cancer-promoting and Alzheimer’s disease-inhibiting properties, while adiponectin has opposing, cancer-inhibiting and Alzheimer’s disease-promoting ability." (PMID 29587359, 2018). "Leptin and adiponectin have definite effects on several of the important genes, gene products and signaling pathways involved in DS, Alzheimer’s disease, and cancer." (PMID 29587359, 2018). "Possible reasons for leptin’s anti-Alzheimer’s disease effects include its ability, shown in mice, to reduce beta and gamma secretase activity, decrease cleavage of APP and decrease accumulation of beta amyloid." (PMID 29587359, 2018). "Leptin levels are elevated in children with DS, but levels decrease with age, supporting the possibility that any protective action of leptin against Alzheimer’s disease declines over time." (PMID 29587359, 2018). "In patients with Alzheimer disease (AD), increased leptin levels in cerebrospinal fluid (CSF) and hippocampal tissue alterations were found at autopsy." (PMID 28278160, 2017). "Leptin levels negatively correlated with the development of Alzheimer’s disease in lean humans, and leptin signaling seems to be dysregulated in Alzheimer’s disease brains." (PMID 27012931, 2016). "An increasing number of epidemiological and experimental studies provide support for the link between leptin and Alzheimer’s disease (AD) pathogenesis." (PMID 25453257, 2015). "Recent evidence suggests a link exists between impaired leptin function and Alzheimer’s disease (AD; Beccano-Kelly and Harvey, 2012)." (PMID 26464986, 2015). "Administration of leptin to transgenic mouse models of AD (Alzheimers disease) reduces neuronal pathology and improves cognitive performance." (PMID 24325936, 2013). "Here we review the evidence that leptin is a potential cognitive enhancer and also examine the possibility of utilising leptin replacement therapy in the treatment of Alzheimer's disease." (PMID 22254146, 2012). "Leptin has been shown to exert neuroprotective effects in ischemia, Parkinson's and Alzheimer's diseases and epilepsy, and systemic administration of leptin decreases infarct volume after focal cerebral ischemia in mice." (PMID 22536415, 2012). "The discovery of leptin’s action in cognition and neuronal survival triggered a strong interest on the possible correlation between leptin levels and neurodegenerative disorders, like the Alzheimer disease (AD)." (PMID 22848520, 2012). "Evidence shows that the insulin-like growth factor-1 (IGF-1) and leptin reduce β-amyloid (Aβ) production and tau phosphorylation, two major hallmarks of Alzheimer's disease (AD)." (PMID 21651786, 2011). "One widely employed model for neuronal cells in culture is the human neuroblastoma line SHSY5Y, which was used to elucidate the role of leptin in Alzheimer's disease." (PMID 20721342, 2010). "In lean humans, leptin levels have been negatively correlated with the development of Alzheimer’s disease." (PMID 21070531, 2010). "Indeed, several studies have indicated the role of chronic low-grade inflammation in neurodegenerative disorders such as Alzheimer’s disease (AD) and Parkinson’s disease (PD), in which the role of leptin has been highlighted." (PMID 40076884, 2025). "In a third model of Alzheimer’s disease, the TgCRND8 model, leptin has been reported to be effective in ameliorating pathology and cognition, and leptin and lithium appear to share some molecular targets, such as GSK-3beta and PI-3 kinase, and interrelationships." (PMID 39199293, 2024). "This is due to the action of leptin that counteracts multiple harmful events observed in the pathogenesis of Alzheimer's disease, from aberrations in hippocampal synaptic function to changes in the expression of proteins related to the disease and prevention of neuronal death." (PMID 38684691, 2024).
Alzheimer disease (continued). "In PD, reduced expression of leptin and insulin receptors has been found, which might be involved in the pathomechanism of the disease, similarly to Alzheimer’s disease and other neurodegenerative diseases." (PMID 37233709, 2023). "PTP-1B, a regulator of insulin and leptin signalling that has been shown to be involved in multiple Alzheimer's disease processes, was moderately increased in both Dem-Alzheimer's disease (fold-change = 1.39, P = 0.037) and Dem-Other (fold-change = 1.39, P = 0.023) compared with CN individuals." (PMID 35800899, 2022). "Moreover, degeneration is initiated in the TA pathway at very early stages of Alzheimer’s disease, and recent clinical evidence has revealed links between plasma leptin levels and the incidence of Alzheimer’s disease (AD)." (PMID 33440796, 2021). "In addition, the administration of leptin can reduce pathology and improve memory in a transgenic mouse model of Alzheimer’s disease." (PMID 30551684, 2018). "The varying levels of leptin and adiponectin with age may be important in Alzheimer’s disease and cancer pathogenesis." (PMID 29587359, 2018). "Reduced Wnt signaling may increase Alzheimer’s pathology and activation of Wnt may reduce beta-amyloid toxicity; decreased Wnt signaling may thus contribute to Alzheimer’s disease, and leptin might increase Wnt signaling and be neuroprotective." (PMID 29587359, 2018). "Moreover, the results from animal studies demonstrated a role of leptin in memory decline and AD pathology, e.g., showing that treatment of transgenic mouse model of Alzheimer’s disease with leptin led to a reduction of Aβ levels and memory improvement." (PMID 28421328, 2017). "Additionally, in elderly individuals included in the Alzheimer’s Disease Neuroimaging Initiative (ADNI) study, higher leptin levels were associated with deficits in frontal, parietal, temporal and occipital lobes, brainstem, and the cerebellum." (PMID 29156608, 2017). "It was shown in experimental studies that leptin reduced both brain Aβ load and hyperphosphorylated tau in neuronal cells, thus diminishing two important elements of Alzheimer’s disease." (PMID 28421328, 2017). "Furthermore, observational studies have shown that leptin plays a role in cognition and in the pathogenesis of Alzheimer's disease." (PMID 26881138, 2016). "As we said in the Introduction, there is evidence for an involvement of leptin and its functional LepRb receptor in memory formation and possibly reducing the core drivers of Alzheimer’s disease (AD), a very important possibility for our growing population of seniors." (PMID 26184316, 2015). "Several studies support the relation between leptin and Alzheimer’s disease (AD)." (PMID 25453257, 2015). "Indeed, several evidence suggest a neuroprotective role of leptin, which can prevent neuronal death in various neurodegenerative situations, such as models of Parkinson’s disease, Alzheimer’s disease (AD), and models related to epilepsy." (PMID 25352831, 2014). "Leptin has extra-hypothalamic effects that may protect the brain against the development of mood and neurodegenerative disorders, such as Alzheimer’s disease." (PMID 21070531, 2010). "Indeed reductions in the circulating levels of leptin have been detected in Alzheimer's disease patients." (PMID 18024215, 2007). "Moreover, leptin is reported to significantly decrease the levels of amyloid β and to improve memory performance in transgenic mouse models of Alzheimer's disease." (PMID 18024215, 2007). "Frontal: lobe tissue from chronic ethanol-exposed rats had reduced levels of leptin and ghrelin immunoreactivity, corresponding with previous observations in human subjects following ethanol consumption or exposure, and in people with Alzheimer’s disease neurodegeneration." (PMID 41463326, 2025).
Alzheimer disease (continued). "These mice also show diminished leptin-regulated feeding suppression, suggesting a direct impact of leptin on astrocyte development and function in adult mice which is supported by studies demonstrating leptin-mediated neurogenesis post-stroke as well as a model of Alzheimer’s disease in rodents." (PMID 34955895, 2021). "A possible trial could measure vitamin D in DS subjects and follow them over time on vitamin D supplements (if vitamin D is low) to determine the leptin/adiponectin ratio, any change in the ratios and the occurrence of leukemia, solid tumors, and Alzheimer’s disease." (PMID 29587359, 2018). "Furthermore, studies suggest that leptin is neuroprotective, and low leptin levels may play a role in the pathogenesis of neurodegenerative diseases such as Alzheimer's disease (AD) and Parkinson's disease (PD)." (PMID 26881138, 2016). "It is now known that leptin has beneficial effects on both the survival and neurophysiology of the neurons that are lost in Alzheimer's disease suggesting that it may be an important research target in the quest for strategies to prevent, halt, or cure this condition." (PMID 22013440, 2011). "For instance, serum levels of LEP were found to be high in aging and obesity-related diseases like obstructive sleep apnea (OSA) and Alzheimer’s disease." (PMID 31878053, 2019). "Notably, we identified and quantified the mediating roles of 5 mediators between LTL and PCs, namely circulating leptin levels, sex hormone binding globulin levels, liver iron content, naïve CD4–CD8-T cell %T cell, and Alzheimer’s disease." (PMID 38831447, 2024). "Here, we evaluated whether baseline serum leptin and adiponectin levels could predict the development of silent brain infarcts in subjects with MCI and AD from the Alzheimer’s Disease Neuroimaging Initiative (ADNI) cohort." (PMID 38686200, 2024). "Thus, in the review by McGregor and Harvey it is found that in transgenic mouse models of Alzheimer’s disease (CRND8), leptin improved performance in object recognition, contextual, and fear-conditioned tasks." (PMID 35563589, 2022). "The have been experimentation reports that leptin may prevent cortical atrophy, but also amyloid accumulation and hyperphosphorylation of TAU peptides —two hallmarks of Alzheimer’s disease." (PMID 30893833, 2019). "Importantly, LTL remains an independent risk factor for PCs, suggesting that the impact of downstream mediators, including circulating leptin levels, sex hormone binding globulin levels, liver iron content, naïve CD4–CD8-T cell %T cell, and Alzheimer’s disease, on LTL is limited." (PMID 38831447, 2024). "It was shown that obese people are likely to develop leptin resistance, the condition which may attenuate the beneficial action of leptin on the brain and may be responsible for the lack of protective effect of leptin on dementia and Alzheimer’s disease among obese people." (PMID 28421328, 2017). "While we included leptin, IL-6, IL-1β, TNF-α, and CRP, we did not assess other cytokines such as MCP-1, IL-18, or markers of microglial activation and phenotype (e.g., CD68 and sTREM2), which may play significant roles in glial reactivity in Alzheimer's disease." (PMID 40521397, 2025).
prostate carcinoma (89 papers, 2004 to 2025). A carcinoma that arises from epithelial cells of the prostate gland. "Clinical data further associate high leptin levels with increased prostate cancer risk and unfavourable outcomes in ovarian cancer." (PMID 41586225, 2025). "A particularly relevant finding involves the association of combined low adiponectin (<6 μg/mL) and high leptin (>4 ng/mL) levels with a significantly increased risk of biochemical recurrence in prostate cancer patients treated with radical prostatectomy." (PMID 41555998, 2025). "The rest of included biomarkers blood γ-tocopherol level, high-density lipoprotein (HDL), low-density lipoprotein (LDL), leptin, adiponectin, serum C-peptide concentration, and white blood cell count exhibited null association with prostate cancer." (PMID 38489391, 2024). "Definitely, enhanced plasma leptin levels have been well associated with both prostate cancer and testicular cancer in males, and the leptin receptor is a known target for treating these cancers in the male population." (PMID 35628271, 2022). "Conversely higher circulating leptin was negatively associated with prostate cancer risk (OR = 0.61, 95% CI 0.46–0.81)." (PMID 36558416, 2022). "There was little evidence of funnel plot asymmetry in studies of associations of adiponectin or leptin with prostate cancer incidence." (PMID 33431998, 2021). "A meta-analysis of genetic polymorphisms in adiponectin, leptin and their receptors found several associations with prostate cancer risk and aggressiveness." (PMID 33431998, 2021). "There was weak evidence of a small association between leptin and aggressive prostate cancer (overall OR 1.03, 95% CI 1.00 to 1.06 per 2.5 ng/ml increase in leptin, p = 0.02)." (PMID 33431998, 2021). "It is noteworthy to mention that such association between high levels of circulating leptin and prostate cancer is more striking in advanced prostate tumors, thus its use as a potential tumor progression marker should not be ruled out." (PMID 34074045, 2021). "The increased leptin/adiponectin ratios and adipose inflammation are risk factors for the development of prostate cancer in men57,58 and were observed in HFD Inpp4b−/− males." (PMID 33772116, 2021). "Although several in vitro studies have suggested an association between leptin and prostate cancer, the findings of epidemiological studies have been inconsistent." (PMID 33920379, 2021). "We conducted a systematic review and meta-analysis of associations of leptin and adiponectin with overall and aggressive prostate cancer." (PMID 33431998, 2021). "This study revealed that the expression levels of leptin and leptin receptor mRNA are suggested to be the potential biomarkers for risk of prostate cancer." (PMID 32573960, 2020). "Clinically, greater serum levels of leptin and lower levels of adiponectin are associated with prostate cancer initiation and progression." (PMID 28389628, 2017). "In an earlier article, Freedland and Aronson mentioned that leptin is a potential prognostic marker for prostate cancer patients because they found that increased leptin levels in plasma or serum are associated with the development of prostate cancer." (PMID 26852017, 2016). "The present study aimed to clarify the role of genetic variants in leptin, adiponectin and their receptors in prostate cancer." (PMID 27768592, 2016). "Both high levels of leptin in circulation and leptin receptor mutation are associated with prostate cancer risk in human patients; however, the in vivo mechanistic evidence is less conclusive." (PMID 26376613, 2015). "Increased plasma or serum leptin levels have previously been found to be associated with development of prostate cancer." (PMID 23815123, 2013). "A Chinese case-control study provided consistent evidence by finding an approximately two-fold increased risk of prostate cancer in men with the highest tertile leptin level relative to the lowest tertile." (PMID 23593308, 2013).
prostate carcinoma (continued). "In particular, the fat hormone leptin has been shown to be positively associated with prostate cancer." (PMID 22690216, 2012). "Leptin and insulin/IGF-1 are high in obese men and suppress androgen levels, moreover leptin has been implicated in advanced and high-grade prostate cancer in two case–control studies." (PMID 21266978, 2011). "Although several data appeared conflicting, recent studies have clarified the association between leptin and prostate cancer." (PMID 21566743, 2008). "Single nucleotide polymorphism G/A in region—2548 bp of leptin gene was associated with the risk of prostate cancer development and more advanced stage in already developed cancer." (PMID 21566743, 2008). "Moderately elevated plasma leptin concentrations are associated with later development of prostate cancer." (PMID 21566743, 2008). "Serum leptin concentrations show a direct association with prostate cancer risk, and testosterone is a well-known promoter of the growth of both normal prostate tissue and prostate tumors." (PMID 19000315, 2008). "Adipocytokine leptin is associated with various cancers including breast, endometrial, gastric, and prostate cancers." (PMID 21566743, 2008). "The LEP (-2548) A allele, which result in high leptin secretion, was associated with increased risk of prostate cancer." (PMID 16504019, 2006). "Furthermore, higher circulating levels of leptin in prostate cancer patients were found to be associated with an increased risk of larger-volume tumors." (PMID 39642218, 2024). "Regarding prostate cancer, studies have shown that men with moderate levels of leptin may have an increased risk of developing prostate cancer." (PMID 37238961, 2023). "Nonetheless, the same report also highlighted a directionally opposite association between leptin and risk of prostate cancer based on meta-analysis of cross-sectional data, as well as describing a weak, positive link between circulating leptin levels and aggressive disease." (PMID 36558416, 2022). "Hence, after BMI adjustment, BioT was positively associated (OR = 1.32, 95% CI 1.13–1.55) whilst leptin tended to be negatively associated (OR = 0.75, 95% CI 0.56–1.00) with prostate cancer risk." (PMID 36558416, 2022). "Finally, we estimated that the reduction in BioT and increase in leptin plasma concentrations mediated ~21% and ~54%, respectively of the total, genetically determined association between BMI and prostate cancer risk." (PMID 36558416, 2022). "However, the weak association of leptin with aggressive prostate cancer was attenuated when maximally adjusted models were selected over minimally adjusted models." (PMID 33431998, 2021). "Here we systematically review the epidemiological evidence on associations of circulating adiponectin and leptin with overall and aggressive (higher grade and/or more advanced stage) prostate cancer and combine study-specific effect estimates in a dose–response meta-analysis." (PMID 33431998, 2021). "When just the prospective evidence was considered, all pooled effect estimates were consistent with the null hypothesis accept for a weak inverse association between leptin and overall prostate cancer (3% decreased risk per 2.5 ng/ml increase in leptin)." (PMID 33431998, 2021). "Finally, elevated circulating levels of IGF-1, leptin and adiponectin, commonly encountered in MetS patients, have all been associated with prostate cancer risk." (PMID 27386844, 2016). "Third, changes in certain hormones, including testosterone, sex hormone-binding globulin, and leptin, may affect the risk of prostate cancer." (PMID 27652121, 2016). "This is consistent with our previous results in spite of the fact that other authors have demonstrated the pro-proliferative effects of leptin in androgen independent prostate carcinoma cells and a risk association of high leptin levels in circulation with prostate cancer aggressiveness." (PMID 25928422, 2015).